GNAI3 (G protein subunit alpha i3)
Diseases named in the same sentence as GNAI3 in open-access papers:
GNAI3 is named in the same sentence as 53 diseases in open-access papers, as found by Europe PMC text mining. Sharing a sentence is not in itself a finding about the gene and the disease. The quoted sentences say what the papers report.
auriculocondylar syndrome (9 papers, 2016 to 2025). Auriculo-condylar syndrome (ACS) presents with bilateral external ear malformations ('question mark' ears), mandibular condyle hypoplasia, microstomia, micrognathia, microglossia and facial asymmetry. "Dominant missense mutations in Gαi3, the member of the Gαi/o subclass encoded by GNAI3, have been associated with “Auriculocondylar Syndrome-1” (ARCND1; OMIM #602483)." (PMID 40745211, 2025). "Previous studies have implicated variants of the GNAI3 gene in auriculocondylar syndrome (ACS, MIM#602483), a rare AD disorder characterized by micrognathia, mandibular condyle hypoplasia, and question mark auricular malformation." (PMID 36352425, 2022). "GNAI3 has also been identified in the majority of cases of the auriculocondylar syndrome (ACS)." (PMID 28484278, 2017).
colitis (5 papers, 2021 to 2024). Inflammation of the colon. "As for the G protein-related genes, one study reported that GNAI3 reduced colitis-associated tumorigenesis in mice." (PMID 37063924, 2023). "For example, GNAI1 and GNAI3 were found to reduce colitis-associated tumorigenesis in mice through blocking of IL6 signaling and down-regulation of the expression of GNAI2." (PMID 34992636, 2021). "Knockout GNAI1 and GNAI3 in BMDSCs cells can induce phosphorylation of JAK2 and STAT3, promoting colitis-associated tumors in mice." (PMID 39695099, 2024). "GNAI3 is a potential tumor suppressor, which inhibits GNAI2-mediated myeloid-derived suppressor cells (MDSCs) proliferation and Colitis-Associated tumorigenesis by negatively regulating IL6 signaling pathway." (PMID 36042374, 2022).
glioma (5 papers, 2020 to 2024). A benign or malignant brain and spinal cord tumor that arises from glial cells (astrocytes, oligodendrocytes, ependymal cells). "As shown in the LRS formula, the expression of GNAI3, ACACB, ADCY3, and ACADSB emerged as the most important LMRGs that contribute to the risk signature of gliomas patients." (PMID 36860853, 2023). "It should also be noted that the function of KCNC1, KCNT1, RIMS2, NECAP2, GNG5, SCAMP2, GNAI3 genes is also correlated with membrane function in low-grade gliomas." (PMID 37239411, 2023). "Consistently, the protein expression of GNAI3 was higher in the more aggressive high-grade gliomas in the Human Protein Atlas immunohistology study, while that of ACADSB exhibited a reverse trend." (PMID 36860853, 2023). "Consistent with our results, high expression of HDAC1, CASP3, REST, GNAI3, FZD1, EPHB4 was found to correlate with poor prognosis of glioma, and inhibitors of HDAC1 inhibited the EMT process in glioma cells thereby affecting cell migration and invasion." (PMID 38629068, 2024). "In gliomas, overexpression of GNAI1 or GNAI3 appears essential for AKT hyperactivation and tumor growth." (PMID 34321466, 2021). "A total of 18 genes were significantly negatively correlated with DGCR5, including GNAI3, VIM, ITGB1, HIF1A, and HDAC1, all of which are critical factors affecting glioma development." (PMID 33085646, 2020).
depression (4 papers, 2019 to 2024). "Gnai3 is associated with lipid metabolism in major depression and AD pathogenesis in the mouse model." (PMID 39088109, 2024). "In particular, we discovered for the first time that RAB1A, GNAI3, RAB33B, LAMP2, and KIF5B might be potential markers for the diagnosis of depression." (PMID 35559009, 2022).
sarcoma (3 papers, 2021 to 2023). A usually aggressive malignant neoplasm of the soft tissue or bone. "Gnai3, encoded by GNAI3, consists of five highly conserved motifs (G1–G5) that are involved in the rat sarcoma superfamily and G α protein binding to guanosine diphosphate (GDP)/guanosine triphosphate (GTP)." (PMID 36352425, 2022). "Among the seven survival-associated mRNAs, the high expression levels of SMARCC1, SRSF10, PRPF38A, JARID2 and GNAI3 were significantly associated with shorter overall survival in sarcomas (P = 0.0018, P = 0.037, P = 0.0058, P = 0.0093, and P = 0.0234, respectively)." (PMID 33653335, 2021). "The pan-cancer mRNA expression of GNAI3 was higher in breast-invasive carcinomas, cervical squamous cell carcinomas, esophageal carcinomas, head and neck squamous cell carcinomas, glioblastomas, sarcomas, and skin cutaneous carcinomas." (PMID 37894479, 2023). "Among them, high expression levels of SMARCC1, SRSF10, PRPF38A, JARID2, GNAI3, miR-301a-3p, miR-106b-5p, miRNA-130b-3p, miR-423-3p and LINC01296 and low expression levels of ARF3 and PRKCB were associated with shorter overall survival in sarcomas." (PMID 33653335, 2021). "Therefore, the interaction of SNHG12, miR-133a-3p/miR-133b and GNAI3 in sarcoma was worthwhile of exploration." (PMID 33653335, 2021).
colon cancer (2 papers, 2014 to 2022). "GNAI3 is required for autophagy at the sequestration step in human colon cancer cell line HT-29 but GNAI3 deficiency in mouse was also found to enhance the autophagic proteolysis induced by liver perfusion." (PMID 24751948, 2014). "Studies have shown that RGS19 and GNAI3 are engaged in controlling autophagy in human colon cancer HT-29 cells." (PMID 24751948, 2014).
gastric cancer (2 papers, 2024 to 2025). A primary or metastatic malignant neoplasm involving the stomach. "In line with this, previous studies have reported GNAI1 downregulation as a poor prognostic marker in ovarian cancer and GNAI3 suppression associated with metastasis in gastric cancer." (PMID 40819057, 2025). "GNAI3 was identified as a biomarker indicating the relative risk of susceptibility to gastric cancer." (PMID 39000203, 2024).
hepatocellular carcinoma (2 papers, 2019 to 2025). A malignant tumor that arises from hepatocytes. "In hepatocellular carcinoma, high GNAI3 expression has been associated with poor prognosis, potentially through modulation of TGF-β signaling and interaction with immune checkpoint pathways." (PMID 40819057, 2025). "Similarly, reduced expression of GNAI3 was linked to immune evasion and poor prognosis in hepatocellular carcinoma." (PMID 40819057, 2025). "A few prior studies have implicated GNAI3 in immune cell recruitment and PD-L1 expression regulation in hepatocellular carcinoma, but no studies have mapped GNAI genes to immune subtypes or interactions in COAD." (PMID 40819057, 2025). "In addition to CRC, tumor cell migration and invasion is inhibited by the Guanine nucleotide binding protein, alpha inhibiting activity polypeptide 3 (GNAI3), in hepatocellular carcinoma." (PMID 31552190, 2019).
adrenal cancer (1 paper, 2021). A carcinoma involving a adrenal gland. "In other cases, such as with GNAI3, an increase in gene expression was reported in nutrient starved adrenal glands in a mouse model, starvation that is often observed in adrenal cancer." (PMID 34572898, 2021).
breast carcinoma (1 paper, 2019). "Network analysis on the cancer genome atlas (TCGA) breast cancer dataset revealed interaction between CXCL12 and CXCR7 (ACKR3), and a number of G-protein family members (GNG5, GNB4, GNB2, GNG12, GNG7, GNGT1, and GNAI3)." (PMID 30993013, 2019).
cervical cancer (1 paper, 2022). A primary or metastatic malignant neoplasm involving the cervix. "TCGA and the Genotype-Tissue Expression (GTEx) databases reveal that the number of Gαi3 (GNAI3) mRNA transcripts in cervical cancer tissues (“Tumor”, n= 306) was remarkably higher than it in normal cervical tissues (“Normal”, n = 13)." (PMID 36263185, 2022).
cocaine addiction (1 paper, 2022). "There were 13 genes enriched in cocaine addiction and the circadian entrainment signaling pathway (Bdnf, Gnai1, Gnai3, Grin2d, Grm2, Maob, Cam2, Camk2g, Gng12, Mapk1, Pcb4, Prkm2, and Pdyn)." (PMID 36164400, 2022).
dyslipidemia (1 paper, 2023). "FAIM2 is linked to obesity and dyslipidemia in the Chinese population, while GNAI3 is associated with non-alcoholic fatty liver disease (NAFLD)." (PMID 37620670, 2023).
Micrognathia (1 paper, 2021). Developmental hypoplasia of the mandible. "Here, we report a novel variant of GNAI3 (NM_006496:c.807C>A:p.(Asn269Lys)) in a Japanese girl with micrognathia using trio-based whole exome sequencing analysis." (PMID 33723370, 2021).
ocular albinism (1 paper, 2016). Albinism affecting the eye in which pigment of the hair and skin is normal or only slightly diluted. "Summary of variants in exons of GNAI3 with likely functional effects in patients diagnosed with ocular albinism." (PMID 27607449, 2016). "Summary of deletions and insertions in the first 2109 bp of the GNAI3 non-coding exon 9/3’ UTR in patients affected with ocular albinism." (PMID 27607449, 2016). "We found 258 SNVs in the GNAI3 gene from the subjects with ocular albinism that were also observed in the unaffected, unrelated control DNA samples." (PMID 27607449, 2016). "Summary of SNVs, deletions and insertions in GNAI3 introns of patients diagnosed with ocular albinism." (PMID 27607449, 2016). "Summary of SNVs in the first 2109 bp of the GNAI3 non-coding exon 9/3’ UTR in patients affected with ocular albinism." (PMID 27607449, 2016). "Using a combination of HaloPlex and MiSeq sequencing, we identified many variants in the GNAI3 gene that were found only in the DNA of patients diagnosed clinically with ocular albinism but whose DNA had tested negative for OA1 mutations." (PMID 27607449, 2016). "Some of these mutations are pathogenic and can result in a non-functional GNAI3 protein leading to the characteristic phenotype of ocular albinism." (PMID 27607449, 2016). "To test our hypothesis, we have sought mutations in GNAI3 in DNA samples from 26 patients diagnosed with ocular albinism according to clinical parameters but in whom no OA1 mutations had been detected by standard CLIA laboratory sequence analyses." (PMID 27607449, 2016). "Thus, SNVs, deletions, or insertions may affect the 3’ UTR regulatory sequences of GNAI3 and play a role in the expression of the ocular albinism phenotype." (PMID 27607449, 2016). "The F223V mutation, present in Patient 21, does not allow this interaction and thus, the activation of GNAI3, possibly leading to the abnormal phenotypes characteristic of ocular albinism." (PMID 27607449, 2016). "Genetic screening of GNAI3 and eventually of other genes corresponding to proteins (as yet not identified) involved in the OA1 signaling cascade may benefit individuals who present the ocular albinism phenotype but do not have any mutations in OA1." (PMID 27607449, 2016).
pancreatic cancer (1 paper, 2024). "The bioinformatic analysis was performed to evaluate the expression levels of Gαi3 (GNAI3) in human pancreatic cancer utilizing The Cancer Genome Atlas (TCGA) database." (PMID 39349432, 2024).
pilocytic astrocytoma (1 paper, 2025). Pilocytic astrocytoma is a rare subtype of low-grade glioma of the central nervous system characterized by a well circumscribed, often cystic, brain tumor with a discrete mural nodule and long, hair-like projections that extend from the neoplastic astrocytes. "Molecular profiling of pilocytic astrocytoma reveals novel oncogenic drivers such as the GNAI3–BRAF fusion, paving the way for pathway‐specific therapeutic development to advance personalized care." (PMID 40654157, 2025).
somatotropinoma (1 paper, 2014). "Here we sequenced all the coding exons of GNAI1,GNAI2 and GNAI3 in a set of young sporadic somatotropinoma patients and familial index cases, thus in patients with a disease phenotype similar to that observed in AIP mutation carriers." (PMID 25291362, 2014). "Here, we have analyzed the coding regions of GNAI1,GNAI2, and GNAI3 in a set of young sporadic somatotropinoma patients (n = 32; mean age of diagnosis 32 years) and familial index cases (n = 14), thus in patients with a disease phenotype similar to that observed in AIP mutation carriers." (PMID 25291362, 2014).
X-linked ocular albinism (1 paper, 2016). "Thus, we have identified GNAI3 as a second gene possibly responsible for X-linked ocular albinism." (PMID 27607449, 2016).
tumor (15 papers, 2019 to 2025). "Within this dataset, we observed the association in the tumor microenvironment between the gene expression of GNAI subunit 3 (GNAI3) and a poor prognosis." (PMID 37894479, 2023). "However, in this study, we found that GNAI3 mRNA showed a high expression state in LUAD tumor tissues and was associated with poor prognosis, but it showed a completely opposite trend in protein levels." (PMID 36117156, 2022). "In triple-negative breast cancer (TNBC), GNAI3 promotes tumor proliferation and metastasis by facilitating Wnt/β-catenin signaling." (PMID 40819057, 2025). "GNAI3 also regulates lysosomal activity and vesicle trafficking, processes that are increasingly recognized as important in tumor survival and drug resistance." (PMID 40819057, 2025). "GNAI3, though less studied, has gained attention for its roles in tumor development and immune regulation." (PMID 40819057, 2025). "In this study, we present an overview of how GNAI family proteins, particularly GNAI3, influence tumor growth and progression, as well as immune responses, with the potential to function as a cancer biomarker." (PMID 37894479, 2023). "G proteins, including GNAI3, can regulate cell proliferation and survival; both are important in carcinogenesis and tumor progression." (PMID 37894479, 2023). "The involvement of GNAI3 in CPs and tumor progression has promoted additional bioinformatics research into GNAI3." (PMID 37894479, 2023). "To accurately evaluate the influence of AHCYL1 gene in the tumor microenvironments, we screened out three AHCYL1-associated genes (GNAI3, DDAH1, and NDC1) and established a risk score model." (PMID 35578598, 2022). "How the GNAI3 gene affects the biological behavior of tumor malignancy in different cancer backgrounds remains an open question." (PMID 36117156, 2022). "This study was designed based on the hypothesis that members of the GNAI gene family (GNAI1, GNAI2, and GNAI3) play tumor-suppressive roles in COAD and that their downregulation may have diagnostic, prognostic, and therapeutic significance." (PMID 40819057, 2025). "The expression of the GNAI3 protein was higher in the tumor tissues." (PMID 37894479, 2023). "GNAI3 may alter cell migration and invasion, two important mechanisms involved in tumor metastasis, in the context of tumor progression." (PMID 37894479, 2023). "Of these eight genes, four (GNAI3, PCDH7, PSEN1, TNFSF9) were highly expressed in tumor tissues and were associated with poor prognosis, while CD69, SLC11A2, and TLR2 were poorly expressed in tumor tissue and were associated with good prognosis." (PMID 36117156, 2022). "FSCN1, a fascin family member, was recently shown to be associated with tumor invasiveness in ACC and GNAI3 (guanine nucleotide binding protein (G protein), alpha inhibiting activity polypeptide 3) was shown to be increased in nutrient starved adrenal glands in RGS4ko mice." (PMID 34572898, 2021). "Among these, Cpeb3 and Gnai3 have proven functionality as tumor suppressors in HCC." (PMID 31470644, 2019). "This study demonstrates that GNAI1, GNAI2, and GNAI3 may act as tumor suppressors in COAD." (PMID 40819057, 2025). "This study reveals the tumor-suppressive function of GNAI1, GNAI2, and GNAI3 in COAD through genetic, epigenetic, and miRNA-mediated regulation." (PMID 40819057, 2025). "Among these 10 genes HDAC1, CASP3, REST, HMG20B, FZD7,GNAI3, FZD1 and EPHB4 had elevated expression in tumor group compared to the normal group, while KCNJ9 and SCRT1 were decreased." (PMID 38629068, 2024). "We obtained the protein expression data of Purinergic genes GNAI2, GNAI3, GNAO1, P2RX4, P2RX7, and PANX1 in normal tissues and tumor tissues in the UALCAN database." (PMID 38180750, 2024). "The analysis results showed that the expression levels of Purinergic genes GNAI2, GNAI3, P2RX4, P2RX7, and PANX1 were significantly higher in tumor tissues than in normal tissues, consistent with the mRNA expression results." (PMID 38180750, 2024).
tumor (continued). "Differential analysis showed that GNAI3, PCDH7, PSEN1 and TNFSF9 were highly expressed in tumor tissues, while ADM, CD69, SLC11A2 and TLR2 were opposite." (PMID 36117156, 2022). "Among all family members, GNAI2 and GNAI3 demonstrated differential expression levels between the GBM tumor and normal tissue samples, whereas GNAI1 was not significantly or differently expressed." (PMID 37894479, 2023).
cancer (5 papers, 2019 to 2025). A tumor composed of atypical neoplastic, often pleomorphic cells that invade other tissues. "The relevance of GNAI3 as a cancer biomarker is mostly determined by whether its expression or level of activity is consistently associated with certain features of cancer, such as its existence and stage, as well as its response to treatment." (PMID 37894479, 2023). "This analysis revealed the involvement of GNAI3 in critical BPs that can drive cancer progression and motility." (PMID 37894479, 2023). "We investigated GNAI3 expression in various cancer types and its correlation with OS, a poor prognosis, and immune infiltration in GBM using TCGA." (PMID 37894479, 2023). "Based on the IHC staining and differential expression between normal and cancer tissues, we focused on GNAI3 for further analysis." (PMID 37894479, 2023). "Furthermore, GNAI3 has been shown to influence the expression of PD-L1 in certain cancer models, suggesting a possible role in immune escape mechanisms." (PMID 40819057, 2025). "Therefore, we focused on GNAI2 and GNAI3 because they demonstrated a higher expression in GBM than in the other cancer types." (PMID 37894479, 2023). "Combined with the existing data, the GNAI3 gene does have an impact on the migration ability of cancer cells, but the molecular mechanism is still fully unknown." (PMID 36117156, 2022). "The GNAI3 protein may be involved in various cancer-related processes." (PMID 37894479, 2023). "Notably, there are not many reports on the functional studies of the GNAI3-encoded protein in cancer." (PMID 36117156, 2022). "GNAI3, however, showed no major enrichment in key cancer pathways." (PMID 40819057, 2025).
bacterial infections (1 paper, 2024). "GNAI1 and GNAI3 regulate cytokine responses to bacterial infections." (PMID 38881758, 2024).
neurological disorders (1 paper, 2025). "As a key regulator of G protein-coupled receptor signaling, Gnai3 has been implicated in the modulation of neuronal excitability and synaptic transmission, and its dysregulation has been linked to various neurological disorders." (PMID 40493342, 2025).
GNAI3 also shares sentences with these, for which no sentence is quoted: amyotrophic lateral sclerosis (1 paper); atherosclerosis (1); autism (1); bipolar disorder (1); brain cancer (1); branchiooculofacial syndrome (1); breast-invasive carcinomas (1); cervical squamous cell carcinoma (1); Cushing syndrome (1); esophageal carcinomas (1); frontotemporal lobar degeneration (1); head and neck squamous cell carcinoma (1); infection (1); inflammatory bowel disease (1); intracerebral hemorrhage (1); lung carcinoma (1); mandibulofacial dysostosis (1); melanoma (1); Myocardial fibrosis (1); neurodegenerative disease (1); non-alcoholic fatty liver disease (1); Obesity (1); ovarian carcinoma (1); pituitary adenoma (1); psychiatric disorder (1); rheumatoid arthritis (1); schizophrenia (1); type 1 diabetes (1); type 2 diabetes (1); vascular dementia (1).